FOXN1 (forkhead box N1)
Description:
Transcriptional regulator which regulates the development, differentiation, and function of thymic epithelial cells (TECs) both in the prenatal and postnatal thymus. Acts as a master regulator of the TECs lineage development and is required from the onset of differentiation in progenitor TECs in the developing fetus to the final differentiation steps through which TECs mature to acquire their full functionality. Regulates, either directly or indirectly the expression of a variety of genes that mediate diverse aspects of thymus development and function, including MHC Class II, DLL4, CCL25, CTSL, CD40 and PAX1. Regulates the differentiation of the immature TECs into functional cortical TECs (cTECs) and medullary TECs (mTECs). Essential for maintenance of mTECs population in the postnatal thymus. Involved in the morphogenesis and maintenance of the three-dimensional thymic microstructure which is necessary for a fully functional thymus. Plays an important role in the maintenance of hematopoiesis and particularly T lineage progenitors within the bone marrow niche with age. Essential for the vascularization of the thymus anlage. Promotes the terminal differentiation of epithelial cells in the epidermis and hair follicles, partly by negatively regulating the activity of protein kinase C (By similarity). Plays a crucial role in the early prenatal stages of T-cell ontogeny.
Synonyms: RONU; WHN; FKHL20; TIDAND; TIDTA; TLIND
Tractability: PROTAC: ubiquitination databases record sites on it.
Gene: Protein-coding gene on chromosome 17 (28,506,243 to 28,538,900, forward strand). Ensembl gene ENSG00000109101.
Subcellular location: Nucleus
Gene Ontology:
Molecular function: protein binding; DNA-binding transcription factor activity, RNA polymerase II-specific; transcription cis-regulatory region binding; DNA-binding transcription activator activity, RNA polymerase II-specific; DNA-binding transcription factor activity; sequence-specific DNA binding
Biological process: positive regulation of epithelial cell differentiation; animal organ morphogenesis; defense response; epidermis development; regulation of transcription by RNA polymerase II; blood vessel morphogenesis; hemopoiesis; keratinocyte differentiation; lymphoid lineage cell migration into thymus; positive regulation of hair follicle development; positive regulation of transcription by RNA polymerase II; regulation of DNA-templated transcription; regulation of positive thymic T cell selection; T cell homeostasis; T cell lineage commitment; thymus development; thymus epithelium morphogenesis
Cellular component: chromatin; nucleus
Genetic constraint (gnomAD): Loss-of-function variants: 13 observed, 46.77 expected, observed/expected ratio (o/e) 0.28, 90% interval 0.18 to 0.44. The upper end of that interval is the gene's LOEUF score, 0.44, which puts it in group 1 of 6, group 1 being the genes least tolerant of losing a copy. Missense variants: 771 observed, 835.58 expected, observed/expected ratio (o/e) 0.92, 90% interval 0.87 to 0.98. Synonymous variants: 341 observed, 371.39 expected, observed/expected ratio (o/e) 0.92, 90% interval 0.84 to 1.
Gene-disease validity (ClinGen):
ClinGen rates the evidence that FOXN1 causes each of these diseases.
T-cell immunodeficiency, congenital alopecia, and nail dystrophy (semidominant): Definitive. A severe combined immunodeficiency characterized by congenital alopecia, severe T-cell immunodeficiency, and ridging, pitting or curving of all nails that has material basis in homozygous mutation in the FOXN1 gene on chromosome 17q11-q12.
Homologues: Orthologues: chimpanzee FOXN1 (98% identical), macaque FOXN1 (97% identical), dog FOXN1 (91% identical), pig FOXN1 (91% identical), rabbit FOXN1 (90% identical), guinea pig FOXN1 (89% identical), mouse Foxn1 (86% identical), rat Foxn1 (85% identical), tropical clawed frog foxn1 (48% identical), zebrafish foxn1 (33% identical), Drosophila melanogaster jumu (19% identical). Paralogues in human: FOXK2 (15% identical), FOXK1 (15% identical), FOXC1 (13% identical), FOXE1 (13% identical), FOXD1 (13% identical), FOXA2 (13% identical), FOXJ3 (12% identical), FOXE3 (12% identical), FOXM1 (12% identical), FOXD3 (12% identical), FOXD2 (12% identical), FOXD4L1 (12% identical), and 29 more.
Diseases named in the same sentence as FOXN1 in open-access papers:
FOXN1 is named in the same sentence as 102 diseases in open-access papers, as found by Europe PMC text mining. Sharing a sentence is not in itself a finding about the gene and the disease. The quoted sentences say what the papers report.
Immunodeficiency (19 papers, 2012 to 2025). Failure of the immune system to protect the body adequately from infection, due to the absence or insufficiency of some component process or substance. "Autosomal recessive biallelic variants in the FOXN1 gene have been associated with a severe combined immunodeficiency (SCID) phenotype." (PMID 40745660, 2025). "Immunodeficiencies caused by heterozygous FOXN1 mutations have mostly been described as causing pathology by reduced gene dosage of FOXN1 or haploinsufficiency." (PMID 39008056, 2024). "FOXN1 mutation-mediated immune deficiency is typically associated with severe combined immunodeficiency." (PMID 37719786, 2023). "It is known that disruption of FoxN1 function in mice leads to a profound immune deficiency and a hairless phenotype." (PMID 35077450, 2022). "FOXN1 mutation-mediated immune deficiency is typically associated with severe combined immunodeficiency and alopecia universalis (SCID/NUDE phenotypes) with homozygous alterations in human animal models." (PMID 36600823, 2022). "Nude mice with a defective FoxN1 gene mimic the human condition with athymia, severe immune deficiency, and hairless skin." (PMID 26933816, 2016). "This case suggests that previously healthy carriers of heterozygous FOXN1 mutations may be at risk of developing immune dysfunction in later life." (PMID 41230284, 2025). "Indeed, autosomal recessive loss-of-function mutations of FOXN1 in humans is known to result in severe combined immunodeficiency, where patients exhibit athymia, congenital alopecia, and nail dystrophy." (PMID 39008056, 2024). "The clustering of malignancies and infections in this case over a short time period supports the hypothesis of immune dysfunction, whilst also emphasising the importance of longitudinal monitoring for patients with FOXN1 mutations, particularly following cytotoxic therapy." (PMID 41230284, 2025). "Additionally, downregulation of FOXN1 was observed, which has been linked to immunodeficiency." (PMID 39561211, 2024). "Genetic defects in FOXN1 transcription factor result in thymus hypoplasia and severe immunodeficiency in humans." (PMID 38259452, 2023). "An example for this latter group is the “hairlessness with short life expectancy” in FOXN1 mutant cats that involves a severe immunodeficiency, in addition to the missing hair, and thus resembles Foxn1 mutant nude mice and rats." (PMID 28235824, 2017). "Humans with defects in FoxN1 experience thymic atrophy and immune dysfunction, and also alopecia and mental depression." (PMID 26933816, 2016). "Of note, Foxn1−/− mice showed undifferentiated TECs responsible for a blockage of thymopoiesis and severe immunodeficiency." (PMID 23874334, 2013). "Thymus-deficient mice were reported to be viable until the adult stage, have immunodeficiency owing to a lack of thymus and peripheral mature T cells, and have disrupted hair growth caused by the Foxn1 gene." (PMID 38724644, 2024). "Mice absent FoxN1 expression, known as athymic nude mice, are without a functional thymus gland and consequently suffer premature aging and susceptibility to infections and cancer associated with immune dysfunction." (PMID 26933816, 2016). "The Nude/SCID immunodeficiency is much more severe than DGS, indicating that the FOXN1 expression is absolutely required for an efficient production of mature T cells." (PMID 22474479, 2012). "Foxn1-knockout mice show congenital hairlessness, severe immunodeficiency and a rudimentary thymus with a lack of T-cell development." (PMID 28350299, 2017).
athymia (15 papers, 2011 to 2025). "Thymus transplantation is indicated for the treatment of athymia and associated T cell deficiency in patients with DiGeorge syndrome, atypical (Omenn-like) phenotype, and FOXN1 deficiency." (PMID 37585915, 2023). "This mutant is transcriptionally inactive and acts as a dominant negative factor displacing wild-type FOXN1 from condensates and causing athymia and severe lymphopenia in heterozygotes." (PMID 34860543, 2021). "In rodents referred to as the “nude locus,” genetic disruption of Foxn1 causes athymia and hairlessness in mice and rats, and a number of TC immunodeficiency syndromes have been linked to the human ortholog." (PMID 34596321, 2021). "Loss-of-function mutation of Foxn1 results in athymia and nude phenotype because of defects in hair follicle formation." (PMID 31937817, 2020). "FOXN1 mutations lead to athymia and result, in humans, in a SCID phenotype, referred as the human equivalent of the mice Nude/SCID syndrome." (PMID 24349129, 2013). "Mutations in FOXN1 lead to athymia together with total alopecia, due to the additional role of FOXN1 in hair follicle differentiation." (PMID 22590644, 2012). "FOXN1 mutations in humans and mice give rise to the “nude” phenotype, which is marked by athymia." (PMID 31914405, 2020). "In order to distinguish our injected mouse MC3T3-E1 cells from the endogenous mouse osteoblasts, we exploited the knowledge that homozygous Nu/Nu mice have a spontaneous mutation in the Forkhead Box N1 (FOXN1) gene (resulting in hairlessness and athymia), and thus are deficient for FOXN1." (PMID 30813947, 2019). "Loss-of-function mutations in the forkhead box N1 (FOXN1) gene lead to nude severe combined immunodeficiency, a rare inherited syndrome characterized by athymia, severe T cell immunodeficiency, congenital alopecia, and nail dystrophy." (PMID 33606990, 2021). "Foxn1 expression is believed to be restricted to keratinocytes in the skin and epithelial stromal cells in the thymus, consistent with the alopecia and athymia seen in naturally occurring or induced models of Foxn1 mutation." (PMID 27880796, 2016). "The thymus is the primary organ able to support T cell ontogeny, abrogated in FOXN1−/− human athymia." (PMID 24349129, 2013). "Knock-out (KO) of the Foxn1 (Forkhead box protein N1) gene results in two well-known, yet independent, defects in mice: hairlessness and athymia." (PMID 23696871, 2013). "Given the rarity of FOXN1 deficiency, the underlying factors contributing for the sustainability of the thymus allograft could be investigated in future studies on immunological reconstitution upon thymus transplantation in cases of DiGeorge syndrome with athymia." (PMID 22590644, 2012). "The Foxn1 null phenotype of severe athymia results from a complete early block in thymus development and has limited understanding of the role of Foxn1 later in ontogeny." (PMID 22072979, 2011). "The resultant mutant FOXN1 protein lacks transcriptional activity, whilst also displacing wild-type FOXN1 from condensates, leading to a dominant negative effect, with resultant athymia and severe lymphopenia." (PMID 41230284, 2025). "Although Δ550 FOXN1 apparently behaved as a loss-of-function mutant for transcriptional activation, its heterozygosity causing athymia was not explained by these results." (PMID 34860543, 2021). "The lack of functional FOXN1 protein expression in humans as well as in other vertebrates causes congenital alopecia universalis, nail dystrophy, and athymia—the so-called “nude” phenotype." (PMID 31914405, 2020). "Investigation of a patient with a rare homozygous FOXN1 mutation (R255X), leading to alopecia universalis and thymus aplasia, unexpectedly revealed non-maternal circulating T-cells, and, strikingly, large numbers of aberrant double-negative αβ T-cells (CD4negCD8neg, DN) and regulatory-like T-cells." (PMID 22590644, 2012).
athymia (continued). "In support of this, murine thymopoiesis actively contributes to the peripheral lymphocyte compartment throughout life in contrast to human thymopoiesis, which may explain why the orthologous Δ505 FOXN1 mouse model does not completely recapitulate the degree of athymia seen in human patients." (PMID 34860543, 2021).
T-cell immunodeficiency (15 papers, 2013 to 2025). A broad classification of disorders that affect the cell-mediated aspect of the immune response. "Foxn1 promoted T-cell development in the early embryos, and its mutation is closely linked to T-cell immunodeficiency." (PMID 38787121, 2024). "Forkheadbox N1 (FOXN1) gene mutation in humans is a rare cause of thymic hypoplasia and T cell immunodeficiency." (PMID 36600823, 2022). "In human patients, loss-of-function mutations in the FOXN1 gene lead to a well-described phenotype of nude combined immunodeficiency, which includes congenital alopecia, nail dystrophy, and T cell immunodeficiency." (PMID 33606990, 2021). "Nude SCID caused by FOXN1 deficiency should be suspected in infants presenting with severe T-cell immunodeficiency associated with congenital AU and nail dystrophy." (PMID 28077132, 2017). "In Foxn1−/− nude animals, initial formation of the primordial organ is arrested and the primordium is not colonized by hematopoietic precursors, causing a severe primary T cell immunodeficiency." (PMID 23874334, 2013). "However, several mutations were identified in this screen, including an abrogated splicing mutation of Exon 6 in the winged-helix transcriptional regulator Foxn1 gene Foxn1 mouse mutants are athymic and severely immuno-compromised, while human FOXN1 mutations cause T-cell immunodeficiency." (PMID 25268389, 2014). "Biallelic mutations causing complete loss of FOXN1 expression and/or function underlie the nude SCID phenotype, named after the association of hairlessness with severe T cell immunodeficiency." (PMID 33257998, 2021). "Nude SCID is also known as FOXN1 deficiency, alymphoid cystic thymic dysgenesis (ORPHA169095), severe T-cell immunodeficiency, congenital alopecia, nail dystrophy syndrome (MIM601705) and Winged helix deficiency." (PMID 28077132, 2017). "Genes central in both mouse networks, include FOXN1 and HESX1, related to T-cell immunodeficiency and septo-optic dysplasia respectively." (PMID 29161290, 2017).
DiGeorge syndrome (12 papers, 2012 to 2024). "Five patients were diagnosed with DiGeorge syndrome, 2 with Ataxia Telangiectasia, 1 with FOXN1 deficiency, and 1 with Coronin 1A deficiency." (PMID 39062699, 2024). "Thus, this technique opens up the possibility of freezing and storing thymus tissue for immediate transplantation into patients with DiGeorge syndrome, FOXN1 deficiency, and atypical (Omenn-like) phenotype." (PMID 37585915, 2023). "Individuals with thymic defects due to 22q11.2 deletion syndrome and FOXN1 haploinsufficiency can have a marked T cell lymphopenia early in life with a gradual normalization of CD4+ and CD8+ T cell numbers possibly due to homeostatic expansion." (PMID 39364398, 2024). "DiGeorges syndrome is caused by a microdeletion of the TBX1-containing chromosome region 22q11.2, nude SCID by mutations in the FOXN1 gene and Otofaciocervical Syndrome type 2 in the PAX1 gene." (PMID 35844523, 2022). "While 22q11.2 deletion-associated with DiGeorge Syndrome (DGS) is the most commonly described genetic defect associated with congenital athymia, FOXN1, PAX1, and others have also been identified as potentially causative." (PMID 33987750, 2021). "Genetic testing and chromosomal microarray can help to identify conditions such as 22q11.2 deletion syndrome (22q11.2 hemizygosity), CHARGE (CHD7 mutations), or FOXN1 deficiency (FOXN1 mutations)." (PMID 33987750, 2021). "Thymic defects, in DiGeorge syndrome (22q11del), CHARGE syndrome (CHD7), and forkhead box protein N1 (FOXN1), can also present with Omenn syndrome." (PMID 35572516, 2022).
alopecia (8 papers, 2012 to 2023). Hair loss usually from the scalp. "Foxn1 deficient mice (nude mice) display HS defects which lead to a fragmentation of HSs and subsequent alopecia in mutant mice." (PMID 30794648, 2019). "Thus, while Foxn1 and Hoxc13 mutations target hair cortex and cuticle alike, the Hq mutant allele causes alopecia by affecting specifically the hair cortex." (PMID 33367954, 2021). "Less common, however, FOXN1 alterations can occur in a heterozygous form and provide a distinct phenotype of severe combined immunodeficiency (SCID) without alopecia." (PMID 36600823, 2022).
lymphopenia (8 papers, 2021 to 2025). Reduction in the number of lymphocytes. "Heterozygous LOF variants in FOXN1 in children can result in less severe susceptibility to infection, low levels of TRECs, and T cell lymphopenia, and one patient was reported with severe thrombocytopenia." (PMID 40842819, 2025). "Patients with heterozygous loss-of-function FOXN1 variants are associated with T cell lymphopenia at birth and low TCR excision circles that can ultimately recover." (PMID 39008056, 2024). "Adults with the same variant had persistent CD8 lymphopenia but improved CD4 counts and reduced susceptibility to infection, suggesting FOXN1 gene dosage is important early in life for CD8 development." (PMID 40842819, 2025). "Heterozygous loss-of-function FOXN1 variants are associated with low TCR excision circles (TRECs) and T cell lymphopenia at birth." (PMID 39008056, 2024). "Haploinsufficiency caused by hypomorphic FOXN1 variants have been associated with T cell lymphopenia and thymic hypoplasia/aplasia and thus may also explain the clinical phenotype of individuals heterozygous for the transcriptionally defective Δ550 FOXN1 variant." (PMID 34860543, 2021). "Importantly, NuRabbits are immunodeficient, characterized predominantly by lymphopenia, similar to that observed in Foxn1 null mice and rats." (PMID 33606990, 2021). "We could show that heterozygous loss-of-function FOXN1 mutations in three pediatric patients not only led to T cell lymphopenia but also a lack of cILC1s, whereas other innate lymphocytes either remained unchanged (cILC3) or even increased (cILC2 and NK cells)." (PMID 40779632, 2025).
severe combined immunodeficiency (8 papers, 2013 to 2024). Severe combined immunodeficiency (SCID) comprises a group of rare monogenic primary immunodeficiency disorders characterized by a lack of functional peripheral T lymphocytes resulting in early-onset severe respiratory infections and failure to thrive. "An inborn null mutation in FOXN1 leads to Nude/severe combined immunodeficiency (SCID) phenotype in mouse, rat, and humans." (PMID 23874334, 2013). "FoxN1 gene expression in the skin, as also seen in the thymus, mutations in the “nude” FoxN1 gene induce the hairless phenotype, associated with a severe combined immunodeficiency (SCID) phenotype." (PMID 32545786, 2020). "The Nude/severe combined immunodeficiency (SCID) phenotype represents the prototype of thymic architecture disruption due to alterations of the FOXN1, which is the master regulator of TE-lineage specification." (PMID 23874334, 2013). "In humans, FOXN1 deficiency leads to a rare form of severe combined immunodeficiency (SCID) with absent or low T cell numbers due to abnormal thymic stroma." (PMID 38455040, 2024). "As the developmental defect of TECs results in a lack of regular T-cell development and selection, FOXN1 deficiency has been classified as a rare form of severe combined immunodeficiency (SCID) with absent or low T-cells (i.e. a T-/lowB+NK+ SCID)." (PMID 28077132, 2017).